RN7SKP219 (RN7SK pseudogene 219)
Gene: Miscellaneous RNA gene on chromosome 10 (21,785,292 to 21,785,587, forward strand). Ensembl gene ENSG00000252634.
Homologues: Orthologues: chimpanzee 7SK (99% identical), guinea pig 7SK (51% identical). Paralogues in human: RN7SKP176 (56% identical), RN7SKP160 (56% identical), RN7SKP187 (56% identical), RN7SKP50 (56% identical), 7SK (55% identical), RN7SKP222 (55% identical), RN7SKP246 (55% identical), RN7SKP251 (55% identical), RN7SKP78 (55% identical), RN7SKP103 (55% identical), RN7SKP185 (55% identical), RN7SKP193 (55% identical), and 284 more.